AR (androgen receptor)
Diseases named in the same sentence as AR in open-access papers (continued):
Sharing a sentence is not in itself a finding about the gene and the disease.
prostate carcinoma (continued). "IL-6 signalling is mediated through the Janus kinase (JAK), signal transducer, activator of transcription 3 (STAT3) and mitogen-activated protein kinase (MAPK), which induces AR-mediated gene activation in prostate cancer." (PMID 15150588, 2004). "This cytokine has been characterised as a prostate exocrine gene product that interacts with its receptor in prostate cells, regulating proliferation and differentiation, and in prostate cancer cell lines activates androgen receptor (AR)." (PMID 15150588, 2004). "Prostate cancer growth is also stimulated by androgens, and can be inhibited by AR antagonists (antiandrogens) or surgical castration." (PMID 12888829, 2003). "Downregulation of AR expression during prostate cancer progression and increased expression with the development of hormone refractory tumours have both been reported." (PMID 12888829, 2003). "The androgen receptor (AR) is important in prostate cancer and BAG-1 increases sensitivity of AR expressing cells to androgens and decreases sensitivity to cyproterone acetate, an anti-androgen used clinically in the treatment of prostate cancer." (PMID 12373595, 2002). "Basic fibroblast growth factor (bFGF), the prototype of heparin-binding growth factors, and the AR are commonly expressed in prostate cancer." (PMID 10638964, 2000). "Interactions between polypeptide growth factors and the androgen receptor (AR) are important for regulation of cellular events in carcinoma of the prostate." (PMID 10638964, 2000). "In summary, these studies show that bFGF is a potent negative regulator of AR protein expression in the human prostate cancer cell line LNCaP." (PMID 10638964, 2000). "Neoadjuvant intense androgen deprivation therapy (ADT) with androgen receptor signaling inhibitors (ARSIs) has shown pathologic complete responses (pCR) in prostate cancer (PCa), but long‐term survival outcomes remain unclear." (PMID 41241930, 2026). "Androgen receptor (AR) is a therapeutic target for prostate cancer." (PMID 42045150, 2026). "For prostate cancer, statins may disrupt lipid rafts, which impairs key signalling pathways including the androgen receptor (AR), EGFR, and PI3K–AKT, thereby reducing tumour growth." (PMID 41583365, 2026). "In agreement with the fact that the AR is a major driver of prostate cancer and is the therapeutic target of ENZ, CIBERSORT analysis showed that AR expression levels negatively correlated with CD8+ T cell infiltration in The Cancer Genome Atlas (TCGA) prostate cancer samples." (PMID 41542764, 2026). "Computed tomography-based evaluation of muscle quality may be useful for predicting the outcome of androgen receptor signaling inhibitors in patients with castration-resistant prostate cancer." (PMID 42053360, 2026). "The AR signaling pathway plays a central role in the development of prostate cancer." (PMID 41743623, 2026). "Leveraging our library of ARTADIs using cultured prostate cancer cells and multiple xenograft models, we reveal that small alterations in the chemical scaffold impact selectivity and potency within the AR-transcriptome; impacting signal transduction pathways involved in protumorigenic mechanisms." (PMID 42045150, 2026). "Taken together, these findings suggest that tumor cell–intrinsic AR signaling may have an immunosuppressive effect within the human prostate cancer TME." (PMID 41486951, 2026). "While androgen receptor (AR) pathway inhibitors such as enzalutamide have demonstrated significant therapeutic efficacy in prostate cancer (PCa) treatment, the inevitable development of acquired resistance continues to pose a major clinical challenge in managing advanced PCa." (PMID 41639054, 2026). "In prostate cancer (PCa), where androgen receptor (AR) is the primary oncogenic driver, epigenetic coregulators, specifically lysine demethylases (KDMs), have previously been identified as factors that alter the transcriptome as cancer cells acquire resistance." (PMID 41870972, 2026).
prostate carcinoma (continued). "The AR blocks prostate cancer cell IFN signaling through suppression of IKKε." (PMID 41542764, 2026). "Given the limited mapping studies in prostate cancer, our aim was to develop mapping algorithms to convert scores from disease-specific questionnaires to EQ-5D utility values for patients receiving novel androgen receptor signaling inhibitors (ARSIs)." (PMID 41551331, 2026). "Additionally, CCL2, secreted by AR-inhibited prostate cancer cells, induces FGF8b secretion from stromal cells within the tumor microenvironment, which in turn enhances KRAS activation." (PMID 42069672, 2026). "We also demonstrated that AR inhibition correlates with enriched immune cell signaling pathways in advanced prostate tumors, using a unique collection of matched biopsies from patients with prostate cancer taken before treatment with enza and upon progression." (PMID 41486951, 2026). "Aberrant androgen receptor (AR) expression is the primary driver of prostate cancer progression." (PMID 41993879, 2026). "Furthermore, inhibition of UHRF1 restored AR pathway activity and re-sensitized resistant prostate cancer cells to enzalutamide." (PMID 41760602, 2026). "Given the use of second-generation AR inhibitors in advanced prostate cancer, we sought to understand whether these agents modify the immune landscape of mCRPC." (PMID 41486951, 2026). "Ongoing phase III trials aim to validate the integration of SBRT with modern systemic therapies, including next-generation androgen receptor pathway inhibitors, to optimize clinical outcomes in hormone-sensitive and castration-resistant oligometastatic prostate cancer." (PMID 42073360, 2026). "Androgen biosynthesis is physiologically necessary for generating the principal stimulus for androgen receptor (AR) signaling and thus plays an essential role for development of the normal prostate, prostate cancer growth, and the development of resistance to hormonal therapies." (PMID 41735769, 2026). "Notably, the expression levels of CDRs and AR in 19 prostate cancer cell lines demonstrated a significant decrease in CDRs in cells exhibiting lower levels of AR." (PMID 41492471, 2026). "We next sought to determine whether the AR suppresses IKBKE mRNA transcription or affects its stability in prostate cancer cells." (PMID 41542764, 2026). "Importantly, the germline risk loci and their target genes uncovered in our study converge on AR pathways, consistent with well-established somatic drivers of prostate cancer." (PMID 41468516, 2025). "Indeed, the primary oncogenic driver and therapeutic target of prostate cancer, the androgen receptor (AR), is a transcription factor." (PMID 40163908, 2025). "Androgen and the androgen receptor play key roles in the treatment of prostate cancer." (PMID 41227614, 2025). "Moreover, various non-coding RNAs have been shown to influence prostate cancer progression by modulating AR signaling, highlighting their potential as biomarkers and therapeutic targets." (PMID 39859417, 2025). "Given the critical role of AR signaling in prostate cancer progression through the modulation of genes essential for cellular proliferation and survival, we investigated whether AR influences ferroptosis by regulating the LTFe-LTF axis." (PMID 40082405, 2025). "Interestingly, knockdown of androgen receptor (AR) in human prostate cancer (PCa) C4-2 cells has been observed to promote CXXC5 expression." (PMID 39806388, 2025). "AKT activation mitigates efficacy of AR targeted therapy in T:E fusion prostate cancer, so these patients may benefit from combination therapy targeting AR and AKT." (PMID 41321318, 2025). "In this particular state, prostate cancer cells are very difficult to destroy as they display lineage plasticity and acquire neuroendocrine traits characterized by the presence of neuroendocrine markers and limited dependence on AR signaling." (PMID 39714760, 2025).
prostate carcinoma (continued). "Androgen receptor (AR) splice variants (AR-Vs) have been described as a potential mechanism of resistance to AR targeted agents (ARTA), e.g. enzalutamide or abiraterone in prostate cancer (PC), eventually leading to castration resistant prostate cancer (CRPC)." (PMID 40859365, 2025). "Although the precise mechanisms by which AR regulates protein translation in prostate cancer remain to be fully elucidated, existing studies suggest that AR may indirectly regulate the mTOR signaling pathway to participate in the protein translation process." (PMID 39963114, 2025). "miR-137 is a potential therapeutic miRNA that, when combined with androgen precursors, can restore the AR-mediated transcription and transactivation axis, maintaining androgenic pathway homeostasis and negatively modulating tumor progression in advanced prostate cancer." (PMID 40722703, 2025). "Additionally, recent studies have demonstrated that the androgen receptor (AR) signaling pathway plays a pivotal role in prostate cancer and engages in complex interactions with the immune microenvironment." (PMID 41357241, 2025). "The androgen receptor (AR) is pivotal for prostate cancer growth and progression." (PMID 39714760, 2025). "More recently, the development of three FDA-approved second-generation AR antagonists, enzalutamide, apalutamide, and darolutamide, has marked significant progress in the treatment of various stages of prostate cancer." (PMID 41020902, 2025). "Consequently, this cascade ultimately inhibits androgen receptor (AR) activity and mitigates the progression of castration-resistant prostate cancer." (PMID 40508992, 2025). "Prostate cancer, the most common cancer in men, progresses from an androgen-dependent to a castration-resistant state driven by androgen receptor (AR) alterations, leading to treatment resistance often enhanced by epigenetic changes and tumor microenvironment interactions." (PMID 41155227, 2025). "The efficacy of these taxanes regardless of AR status suggests they remain valuable options for diverse prostate cancer phenotypes, including AR-negative neuroendocrine variants like ACRJ-PC28." (PMID 41038711, 2025). "Notably, the role of androgens and AR signaling pathways in prostate cancer, the most frequently diagnosed cancer in American men and the second leading cause of cancer-related deaths, is the most studied." (PMID 41228208, 2025). "Therefore, the development of innovative therapeutic strategies that abrogate persistent AR signaling through novel mechanisms of action is an urgent unmet clinical need in prostate cancer medicine." (PMID 39787247, 2025). "The combination of ENZ and the ferroptosis inducer RSL3 was particularly effective in reducing tumor growth in CRPC models, suggesting that targeting AR signaling can potentiate ferroptosis, thereby offering a promising therapeutic avenue for advanced prostate cancer." (PMID 40082405, 2025). "Prostate cancer cells therefore use three independent mechanisms to control AR levels: LSD1-mediated transcriptional repression of AR, E3-mediated degradation of ligand-free AR, and ADP-ribosylation-dependent degradation of androgen-bound AR in association with chromatin." (PMID 40681873, 2025). "To date, no large-scale cohort studies have explicitly correlated AR mutations with leuprolide resistance in prostate cancer." (PMID 40297177, 2025). "In contrast, high-dose androgens facilitate the formation of AR dimers/oligomers to suppress c-MYC expression, inhibit proliferation, and drive a transcriptional program associated with a differentiated phenotype of AR-positive prostate cancer cell lines." (PMID 40150035, 2025). "Additionally, the interaction between PRLR and the androgen receptor plays a critical role in the progression of prostate cancer." (PMID 40978029, 2025).
prostate carcinoma (continued). "YAP was suggested to compete with AR binding to transcription factor TEAD, which diminishes the ability of AR to bind to its promoter and enhancer regions leading to reduced expression of AR markers and consequently slower proliferation of prostate cancer cells." (PMID 40115748, 2025). "Therefore, future comparative studies involving AR-positive and castrate-resistant prostate cancer cell lines are needed to determine the role of the metabolic profile of these cells on the antiproliferative effects of mtG3PDH inhibitors." (PMID 40489535, 2025). "In addition, MC3324, a dual inhibitor of LSD1 and KDM6A/B, increased H3K4me2 and H3K27me3, followed by growth arrest and enhanced apoptosis of prostate cancer cells, downregulation of AR, and impairment of cellular metabolism." (PMID 40940894, 2025). "Similarly, combining the CDK12/CDK13 inhibitor THZ531 with AR inhibition enhanced anti-proliferative and pro-apoptotic activities in androgen-sensitive prostate cancer cells." (PMID 40163908, 2025). "However, prostate cancer cells can evade the effects of NHT through various AR-dependent mechanisms." (PMID 41079787, 2025). "A potentially promising combination therapeutic strategy is combining t-CDK inhibitors with therapies that target sex hormone signalling axes (i.e. AR-targeted therapies in prostate cancer and equivalent therapies targeting the estrogen receptor in breast cancer)." (PMID 40163908, 2025). "AR plays a significant role in the progression and development of prostate cancer." (PMID 40356745, 2025). "One study has evaluated the whole blood-circulating androgen receptor (AR) transcripts of full length (AR-FL) and one of AR-Vs (AR-V1) can serve as blood-based biomarkers for identification of the primary resistance to AA in castration-resistant prostate cancer patients." (PMID 39931089, 2025). "Through the immunohistochemical analysis of autopsy specimens, we demonstrate a significant reduction in pulmonary TMPRSS2 expression in ADT-treated patients compared to untreated prostate cancer patients and controls, with direct AR antagonists showing particularly potent suppressive effects." (PMID 41150771, 2025). "Bavdegalutamide, a proteolysis-targeting chimera (PROTAC) degrader of the androgen receptor (AR), shows promise in prostate cancer treatment, while TAM-IN-2, a TAM receptor inhibitor, effectively blocks Gas6-induced AXL activation and suppresses lung cancer progression." (PMID 40573405, 2025). "Overall, understanding the molecular cross-talk between AR signaling in CAFs and prostate cancer cells could pave the way for novel therapeutic approaches to combat drug resistance and metastatic disease in prostate cancer." (PMID 40008000, 2025). "It is well known that AR inhibitors may lead to initial response in advanced prostate cancer; however, the disease sometimes progress to castration-resistant prostatic cancer (CRPC), and both our patients represent a clear example of such a possibility." (PMID 40895111, 2025). "Androgen receptor (AR) is a hormonal transcription factor (TF) that binds to cis-regulatory elements of prostate lineage-specific genes to govern androgen response and progression of prostate cancer (PCa)." (PMID 41768226, 2025). "Prostate cancer cell growth is frequently driven by androgen receptor activation." (PMID 40563571, 2025).
prostate carcinoma (continued). "Androgen receptor serves as a transcription factor, planning the differentiation of the prostatic epithelium by modulating the expression of hundreds of genes, as well as assuming a vital role in the progression of prostate cancer." (PMID 40271196, 2025). "Membrane-associated AR8 may contribute to the development of castration resistance in prostate cancer by enhancing AR-mediated hormone and growth factor responses." (PMID 40977744, 2025). "However, the impact of ECM stiffness on the androgen receptor (AR), a key target in prostate cancer treatment, remains elusive." (PMID 40115748, 2025). "Although the precise effects on AR levels may vary depending on the cellular context, miR-125b plays a significant role in prostate cancer progression through its modulation of AR-related mechanism pathways." (PMID 40869103, 2025). "The small molecule compound ET516 inhibits the formation of LLPS of wild-type and drug-resistant mutant androgen receptor (AR), which in turn inhibits the transcriptional activity of AR, and ultimately suppresses the tumor growth of prostate cancer cells expressing drug-resistant mutant AR in vivo." (PMID 40642070, 2025). "However, comprehensive mechanistic and preclinical studies in prostate cancer support AR- and MTA1-targeted chemopreventive, interceptive and therapeutic effects of Gnetin C." (PMID 40077738, 2025). "In addition to PSMA’s significance as a therapeutic target, the AR pathway remains the principal driver of prostate cancer progression, as its activation augments the transcription of genes regulating cellular proliferation and metabolism." (PMID 40724999, 2025). "To assess whether TCF19 could be repressed by AR, we treated AR‐proficient human prostate cancer cell lines with the AR agonist dihydrotestosterone (DHT)." (PMID 40952912, 2025). "Moreover, PRDX2 has been shown to promote the progression of prostate cancer by activating the androgen receptor (AR) signaling pathway." (PMID 40281661, 2025). "Enzalutamide is an AR antagonist that blocks androgen receptor signaling in prostate cancer." (PMID 40650173, 2025). "Importantly, this study highlights the potential of Rosmarinus officinalis L. extracts in targeting androgen receptor (AR)-independent pathways in prostate cancer." (PMID 40429793, 2025). "These limitations highlight the need for new approaches and novel targets, including hormone-sparing treatments and non-AR targeted therapies, to better address the varied clinical needs of patients with prostate cancer, particularly those with advanced prostate cancer or mCRPC." (PMID 40627156, 2025). "In addition to common essential genes, genes with known relevance to prostate carcinoma pathobiology, including AR, FOXA1, HOXB13, GATA2, SPOP, and AKT, were depleted." (PMID 40956611, 2025). "Under the therapeutic pressure of NHT, prostate cancer cells may upregulate GR and PR, activating pathways typically stimulated by AR, thereby sustaining tumor cell proliferation and survival." (PMID 41079787, 2025). "Since AR signaling plays a crucial role in prostate cancer progression, these interactions suggest that ALD may effectively disrupt AR-driven pathways, thereby inhibiting PC3 and DU145 cell proliferation and survival." (PMID 39980567, 2025). "Clinical trials with AKT inhibitors, such as ipatasertib and capivasertib, when combined with AR blockade, have demonstrated modest benefits, particularly in PTEN-deficient prostate cancers; however, adverse effects like hyperglycemia and dermatological toxicities limit the therapeutic window." (PMID 40427518, 2025). "However, when androgen levels increase or AR is abnormally amplified, the AR signaling pathway promotes the progression of prostate cancer." (PMID 39963114, 2025). "Moreover, FBS provides cytokines and peptide mediators that activate AR-independent proliferative pathways, enabling the survival of heterogeneous tumor subpopulations frequently observed in advanced prostate cancer." (PMID 41463218, 2025).